NPY (neuropeptide Y)
Diseases named in the same sentence as NPY in open-access papers (continued):
Sharing a sentence is not in itself a finding about the gene and the disease.
prostate carcinoma (continued). "The targets identified based on the integrated analysis of CSMA data and publicly available transcriptomics data displayed high context specificity suggesting GPR160 and NPY likely to be the two most important GPCRs impacting on growth of human prostate and specifically prostate cancer cells." (PMID 21443765, 2011). "The contrast effect of NPY on prostate cancer cell proliferation remains unclear." (PMID 35011543, 2022). "Thus, one major factor expressed by prostate cancer cells and modulating the bone microenvironment may be NPY." (PMID 23390522, 2013). "In another study where authors mined TCGA data, isolating 319 prostate-cancer DEGs enriched in xenobiotic-metabolism pathways, network analysis pinpointed AMACR, FOLH1, and NPY as core hubs." (PMID 40806607, 2025). "Highly expressed genes defining the IDCP cluster, such as MUC6, MYO16, NPY, and KLK12, reflected the aggressive nature of high-grade prostate cancer." (PMID 38732035, 2024). "In another study, the NPY-activated signal was involved in robust proliferation-independent transcriptional changes and ERG rearrangements in prostate cancer." (PMID 35011543, 2022). "The NPY/Y1R system inhibited cancer cell proliferation in LNCaP and DU145 prostate cancer cell lines, but the opposite effect was found in PC3 cells." (PMID 35011543, 2022). "In summary, we found robust population-independent transcriptional changes in prostate cancer and first signs of ERG rearrangements inducing metabolic changes in cancer cells by activating major metabolic signaling molecules like NPY." (PMID 23390522, 2013). "Six target genes were subjected to protein validation: GPR116, NPY and PLA2G7, three genes over-expressed in ERG+ tissues, and AZGP1, HPGD and TFF3, three genes down-regulated in ERG+ prostate cancer tissues." (PMID 23390522, 2013). "NPY (neuropeptide Y) and GPR160 (G protein-coupled receptor 160) were among GPCRs with the highest prostatic tissue level and prostate cancer specificity index." (PMID 21443765, 2011). "In this regard, transcripts of prostate cancer biomarkers, including kallikrein-related peptidase-2 and −3 (KLK2, KLK3), folate hydrolase 1 (FOLH1), and neuropeptide-Y (NPY), were found exclusively in the platelet fraction of cancer patients and were absent in healthy controls." (PMID 39934930, 2025). "We found that NPY in a patient’s blood was not more helpful at diagnosing prostate cancer than the standard prostate-specific antigen blood test." (PMID 39027656, 2024). "Intracellular Ca2+ concentration was not affected by NPY treatment in these three prostate cancer cell lines." (PMID 35011543, 2022). "When we treated prostate cancer cells which do not express endogenous NPY (DU145, LNCaP and PC3) with recombinant NPY (48 h, 25 nM), we observed greater glucose uptake in NPY-treated cells than in untreated cells." (PMID 23390522, 2013).
breast carcinoma (33 papers, 2010 to 2025). "NPY treatment also caused a significant increase in VEGF expression in 4T1 breast cancer cells, in a Y5R-dependent manner." (PMID 38375479, 2024). "NPY can also be applied to patients with osteoporosis caused by breast cancer as Y1R is highly expressed not only in breast cancer but is also positively correlated with osteoporosis." (PMID 34421823, 2021). "A test of interaction of high/low vitamin D levels and breast cancer risk was statistically significant at p < 0.01 for rs198300 (proxy for GWAS rs156299, located upstream of neuropeptide Y [NPY] gene in chromosome 7)." (PMID 29291743, 2018). "However, social isolation increased the risk of cancer development and NPY levels, and in an experimental model of breast cancer, chronic stress increased the extent/frequency of bone metastases." (PMID 37373115, 2023). "In conclusion, neuropeptide Y and its related factors play important roles in breast cancer and osteoporosis development; as such, they may be useful candidates for novel diagnostic and therapeutic strategies for breast cancer and osteoporosis." (PMID 34421823, 2021). "A heterodimer molecule consisting of cyclic RGD and NPY analog motifs in a single probe is an attractive approach, as it targets two receptors that, although expressed differently, play important roles in breast cancer." (PMID 39458969, 2024). "This characteristic has been exploited to develop chemically modified analogs of NPY that are being explored in breast cancer imaging and diagnosis." (PMID 37264315, 2023). "NPY regulated breast cancer development and osteoporosis progression since the osteogenic response was mediated by Y1R/Y2R." (PMID 37373115, 2023). "Neuropeptide Y (NPY) is an abundant neurohormone in human breast carcinomas that acts on a class of G-protein coupled receptors, of which NPY1R and NPY5R are the most highly expressed." (PMID 37264315, 2023). "Neuropeptide Y helps breast cancer cells proliferate and metastasize in part due to its role in angiogenesis via its effects on vascular smooth muscle and VEGF." (PMID 36650218, 2023). "Neuropeptide Y (NPY) analogue [F7,P34]-NPY (YPSKPDFPGEDAPAEDLARYYSALRHYINLITRPRY) was toxic on breast cancer by the human Y1-receptor (hY1R) mediated pathway." (PMID 36794282, 2023). "NPY-targeted nano-scale bubbles were widely applied in ultrasound cavitation chemotherapy of Y1R-overexpressed breast cancer cells." (PMID 37373115, 2023). "This characteristic has been exploited to develop chemically modified analogs of NPY that are used in breast cancer imaging and diagnosis." (PMID 37264315, 2023). "Neuropeptide Y (NPY) acts as cancer suppressors in breast cancer, and the effects are mediated by neuropeptide Y receptors 1 and 5 (Y1R and Y5R)." (PMID 35011543, 2022). "In murine mammary carcinoma 4T1 cells, NPY was shown to promote a concentration-dependent increase in proliferation through increased phosphorylation of ERK1/2." (PMID 35011543, 2022). "Two SNPs in two genes (MBOAT rs13272159 and NPY rs16131) showed an effect modification on the association between IGF-1 serum concentration and breast cancer risk (Pinteraction < 0.05, adjusted Pinteraction < 0.20)." (PMID 35115550, 2022). "NPY is a pleiotropic gene initially thought to be an endogenous anxiolytic peptide whose expression can be regulated by stress; however, NPY has been found to promote the growth and migration of breast cancer cells in recent years." (PMID 36437939, 2022). "Recent studies have tried to utilize NPY in cancer imaging and therapy, focusing on breast cancer first." (PMID 36010960, 2022). "In this paper, the relationship between breast cancer and osteoporosis, the influence of NPY on both diseases, and the recent progress in the research and treatment of these diseases are reviewed." (PMID 34421823, 2021).
breast carcinoma (continued). "We further discuss the relationship between breast cancer and osteoporosis, particularly regarding the influence of NPY on both diseases and how it applies their treatment." (PMID 34421823, 2021). "Hypermethylation of NPY has been described in several cancers, including renal cell carcinoma, breast cancer, and colorectal cancer." (PMID 29682090, 2018). "NPY promoted the proliferation and migration of breast cancer cells and angiogenesis." (PMID 37373115, 2023). "Activation of Y5R increases breast cancer cell chemotaxis towards NPY, proliferation and motility." (PMID 36583743, 2023). "Among them, NPY1R is the only receptor with a high incidence in human breast carcinomas, however it is unclear whether the NPY is locally synthesized in breast tissue or endogenously expressed by breast cancer cells." (PMID 35121782, 2022). "Neuropeptide Y has been found to promote proliferation and migration in breast cancer cells." (PMID 34650974, 2021). "Several applications of NPY in the treatment of breast cancer." (PMID 34421823, 2021). "Additionally, NPY has recently been found to play a role in the progression of breast cancer and osteoporosis." (PMID 34421823, 2021). "Due to the recent advances in NPY research related to breast cancer and osteoporosis, many researchers have begun to ask whether NPY can be used as a potential new strategy for the diagnosis or treatment of breast cancer or osteoporosis." (PMID 34421823, 2021). "The inhibitory action exerted by NPY on estradiol-stimulated growth of estrogen receptor-positive breast cancer cells was mediated by Y1R, and its expression could be used as a biomarker for survival/endocrine sensitivity in estrogen receptor-positive breast cancer patients." (PMID 37373115, 2023). "The study also assessed the targeting of 99mTc-BRL with two breast cancer cell lines xenografts: estrogen receptor-positive (MCF-7, expressing both NPY and αVβ3 receptors) and triple-negative (MDA-MB231, expressing high in αVβ3 and low in NPY)." (PMID 40869454, 2025). "NPY has also been shown to enhance the expression and secretion of VEGF, contributing to angiogenesis and promoting breast cancer progression." (PMID 38375479, 2024). "The tumor-targeting properties of [99mTc]HYNIC-cRGDfk-NPY were examined in vitro using MDA-MB-231 and MCF-7 breast cancer cell lines." (PMID 39458969, 2024). "Recently, our group demonstrated that NPY1R and NPY5R mRNA abundance is induced by the HIFs, sensitizing hypoxic cells to NPY-stimulated motility and proliferation in MCF7 and MDA-MB-231 breast cancer cells." (PMID 37264315, 2023). "Based on these findings, Khan and colleagues developed an analogous of the neuropeptide Y (NPY) and, after labeling it with [99mTC], they tested it for imaging of Y1R in four breast cancer patients showing different stages of disease." (PMID 31652624, 2019). "Neuropeptide Y (NPY) enhances the expression of VEGF and its secretion promoting angiogenesis and breast cancer progression." (PMID 29334991, 2018). "For example, two breast cancer cell lines MDA-MB-231 and MCF-7 exhibit increased motility and invasion in response to NPY, which could be blocked with pharmacological NPY1R and NPY5R antagonists." (PMID 40073121, 2025). "NPY favors breast tumor cell proliferation/migration and angiogenesis, whereas Y5R antagonists (e.g., CGP71683A) not only decreased the cell growth/migration of these cells but also promoted the death of breast cancer cells." (PMID 37373115, 2023). "NPY-stimulated VEGF secretion and production contribute strongly to angiogenesis activity in human breast cancer, and it is also a promoter of prostate and breast cancers, influencing the proliferation and migration of cells." (PMID 34600545, 2021). "The high density and incidence of Y1 receptors in invasive and metastatic breast cancers, also expressing Y2 but not Y4 and Y5 receptors, make these neoplasms important targets for diagnosis and therapy with NPY-related drugs." (PMID 22214201, 2011).
breast carcinoma (continued). "Another study created Y1 receptor ligand (NPY)-modified bubbles, finding that, compared with modified bubbles without NPY targeting, NPY-modified bubbles group showed a high tumor suppression effect and a prolonged survival time in Y1 receptor-overexpressed breast cancer treatments." (PMID 34307371, 2021). "For example, primary tumors and metastatic sites were observed in breast cancer patients treated with a technetium-99 m labeled [F7, P34]-NPY (neuropeptide Y) conjugate, but no peptide uptake was observed in healthy individuals." (PMID 37373115, 2023).
schizophrenia (30 papers, 2008 to 2025). A major psychotic disorder characterized by abnormalities in the perception or expression of reality. "Previous studies have suggested that there were associations between Neuropeptide Y and schizophrenia." (PMID 39691787, 2024). "In humans, the NPY -485T promoter allele was shown to be associated with schizophrenia susceptibility due to a decreased level of neuropeptide in the brain; it is worth noting that memory defects are common in schizophrenia." (PMID 38254919, 2023). "The dysfunction of neuropeptide signaling pathways acting through GPCRs, such as neuropeptide Y or substance P, has also been implicated in schizophrenia and PKA signaling abnormalities." (PMID 38248228, 2023). "The polymorphism of NPY gene and the efficacy of antipsychotic drugs in patients with schizophrenia need further study." (PMID 36339882, 2022). "The pathogenesis of schizophrenia is associated with neuropeptide Y (NPY) gene polymorphism to explore the relationship between rs16141, rs16145, and rs5573 polymorphisms in the NPY gene and antipsychotics response in the Chinese population." (PMID 36339882, 2022). "Evaluation of NPY gene expression and detection of NPY variants could be the next step, which would be more helpful to study the pathogenesis of schizophrenia." (PMID 39691787, 2024). "In the adult human brain, we found that IL-6 may form an interacting community with other proteins differentially overexpressed in the MTG, including CCK and NPY, which are also implicated in schizophrenia and other mental illnesses." (PMID 35353173, 2022). "Beyond that, several other neurotransmitters and neuropeptides, including oxytocin, serotonin, cortisol, GABA, cannabinoid, neuropeptide Y, neurotensin, cholecystokinin, corticotropin-releasing factor, and orexin, have been implicated in the neuropathophysiology of schizophrenia." (PMID 35806096, 2022). "Therefore, this study selected the single nucleotide polymorphism sites of NPY gene that have been reported in previous studies related to schizophrenia, and explored their association with the efficacy of antipsychotic drugs in Chinese Han population." (PMID 36339882, 2022). "Based on the fact that NPY gene is an important schizophrenia susceptibility gene and may be associated with the efficacy of antipsychotic drugs, this study chose to explore the association between NPY gene polymorphisms and the efficacy of antipsychotic drugs." (PMID 36339882, 2022). "The NPY gene may be associated with schizophrenia, impulsivity, aggression and bipolar disorders." (PMID 18992145, 2008). "Researchers also found reduced expression of NPY in the prefrontal cortex of schizophrenia patients." (PMID 39691787, 2024). "We recruited 115 first-episode schizophrenia patients and 58 matched healthy controls, and measured serum Neuropeptide Y levels of them at baseline and again after 10 weeks of risperidone treatment in patient group." (PMID 39691787, 2024). "After treatment of quetiapine, the NPY level in cerebrospinal fluid (CSF) of schizophrenia patient increased." (PMID 39691787, 2024). "The study on the brain of schizophrenia patients indicated that, compared with healthy controls, the proportion of NPY neurons in the upper layers of cortex was lower while the expression was abnormally increased in the deep white matter." (PMID 39691787, 2024). "A mouse experiment further confirms the idea that NPY indicate changes related to schizophrenia through the dopamine pathway." (PMID 39691787, 2024). "Another significant finding of our study is sexual heterogeneity in the effect of NPY on schizophrenia." (PMID 39691787, 2024). "This study investigated relationships between Neuropeptide Y levels and severity of psychiatric symptoms in first-episode schizophrenia patients, and explore the sexual heterogeneity in them." (PMID 39691787, 2024). "Many studies have shown that plasma NPY levels increase after antipsychotic treatment in patients with schizophrenia." (PMID 36339882, 2022).
schizophrenia (continued). "A follow-up study showed that the level of NPY in the cerebrospinal fluid (CSF) of patients with schizophrenia was related to longitudinal outcome, and NPY levels was also related to the Social Competence of the patients." (PMID 36339882, 2022). "After 4 weeks of olanzapine treatment, the plasma NPY content of schizophrenia patients was higher than that before treatment." (PMID 36339882, 2022). "In the schizophrenia study, the messenger RNA and peripheral protein of the NPY gene were different between schizophrenics and healthy subjects." (PMID 36339882, 2022). "Studies have found decreased NPY mRNA expression in the prefrontal cortex of the brain in patients with schizophrenia." (PMID 36339882, 2022). "We used immunohistochemistry and qPCR for CR and NPY in six patients with schizophrenia and six control subjects." (PMID 33281566, 2020). "Together these findings indicate that deficits in NPY expression in the PFC are observed in both schizophrenia and bipolar disorder." (PMID 33192369, 2020). "Several pharmacological studies from our group previously demonstrated that atypical antipsychotic drugs, such as olanzapine, significantly increased both NPY mRNA and protein expression levels in a schizophrenia mouse model." (PMID 32655360, 2020). "The NPY system has been implicated in schizophrenia by post-mortem human studies, which found decreased NPY in the cortex of schizophrenia and bipolar disorder patients." (PMID 25762938, 2015). "Changes in NPY have been observed by some post-mortem investigations in schizophrenia and bipolar disorder and are therefore of interest." (PMID 23805071, 2013). "Previous studies reported decreased NPY levels in the temporal cortex of schizophrenia and decreased NPY receptor gene expression in lymphocytes of schizophrenia." (PMID 18992145, 2008). "Higher NPY levels were observed in patients with first-episode schizophrenia." (PMID 39691787, 2024). "Serum NPY levels were significantly higher in patients with first-episode schizophrenia." (PMID 39691787, 2024). "For example, in the DISC1(disrupted-in-schizophrenia 1) model, which is the candidate gene locus first described in a large Scottish family, NPY-immunoreactive neurons expressions in the prefrontal lobes of DISC1-knockout mice were decreased compared to wild type." (PMID 39691787, 2024). "Neuropeptide Y plays a significant role in the pathogenesis of schizophrenia." (PMID 39691787, 2024). "NPY levels of medication-naïve chronic schizophrenia patients was higher than controls." (PMID 39691787, 2024). "Demographic characteristics and NPY levels of schizophrenia and control group." (PMID 39691787, 2024). "We speculate that there may be a relationship between sex and NPY in schizophrenia, but there is a dearth of studies related to this field, indicating that we need more efforts to make it clear." (PMID 39691787, 2024). "NPY plays a significant role in the pathogenesis of schizophrenia." (PMID 39691787, 2024). "The most important finding of our study is that NPY may be used as a predictor of the severity of schizophrenia symptoms." (PMID 39691787, 2024). "The aim of this study was to determine whether the NPY gene in schizophrenia affects antipsychotic treatment outcomes in Chinese Han population." (PMID 36339882, 2022). "There is growing evidence that NPY plays an important role in the pathophysiology of schizophrenia." (PMID 36339882, 2022). "The neuropeptide Y (NPY) gene is a candidate gene for schizophrenia research." (PMID 36339882, 2022). "In addition, multiple candidate genes implicated in schizophrenia or other psychiatric disorders were detected, such as SST, NPY, SLC32A1, HINT1, RELN, and IFITM3." (PMID 29958387, 2018). "Consistent to the current results, mRNA levels of SST in the PFC are decreased in schizophrenia patients in a study using in situ hybridization and another microarray study reported that both SST and NPY expression levels are decreased in the PFC of schizophrenia." (PMID 18992145, 2008).